IL2 (interleukin 2)
Diseases named in the same sentence as IL2 in open-access papers (continued):
Sharing a sentence is not in itself a finding about the gene and the disease.
cancer (continued). "Pilot clinical trials of adoptive T cell immunotherapy were initiated in cancer soon after the discovery of IL-2 (in the late 1970s), which enabled large-scale culture of T cells." (PMID 19272130, 2009). "This demonstratesthe antagonistic relationship that exists between the affects of IL-2 and IL-21on CTLs with respect to cancer." (PMID 19277104, 2008). "Future clinical studies that are conceptually appealing include an examination of the efficacy of DAB/IL2 in several cancer types and the potential utility of combination therapy with vaccines or other immune enhancing agents such as interferon-α." (PMID 18334033, 2008). "In cancer patients, IL-2 immunotherapy led to expansion of Tregs with potent suppressive activity in vitro." (PMID 18827929, 2008). "Suchfindings are vital to adoptive immunotherapy and its implications in cancer.The potential for immune-related therapy in the treatment of cancer meritsfurther investigation into the interplay between IL-2 and IL-21." (PMID 19277104, 2008). "Adherent NK (A-NK) cells constitute a subset of IL-2-stimulated NK cells which show increased expression of integrins and the ability to adhere to solid surface and to migrate, infiltrate, and destroy cancer." (PMID 17105663, 2006). "Lymphocytes from donors and cancer patients were of similar phenotype after 15 days in culture with 150 UI IL-2." (PMID 15987427, 2005). "Immunotherapy has become a standard approach for cancer management, through the use of cytokines (eg: interleukin-2) and monoclonal antibodies." (PMID 15862126, 2005). "Cancer patients, given high doses intravenously of the cytokine interleukin-2, have symptoms of fever, malaise, nausea, vomiting, and diarrhea, similar to SE food poisoning." (PMID 15498154, 2004). "Inflammatory cytokines such as interleukin-2 (IL-2) and interleukin-12 (IL-12) have been explored for the treatment of cancers." (PMID 12771934, 2003). "NK cells are believed to contribute to the clinical efficacy of cancer immunotherapy using IL-2 in humans." (PMID 12107842, 2002). "In vitro zinc increases IL-2 production from peripheral blood mononuclear cells (PBMCs) of cancer patients." (PMID 9888464, 1999). "Metabolic labelling followed by immunoprecipitation and Western blot results showed that IL-2 in carcinomas was identical to that in human lymphocytes." (PMID 10555752, 1999). "Interleukin (IL-2) and IL-2Rβ/γ have been shown to be expressed in human carcinomas in culture and in situ." (PMID 10555752, 1999). "Despite the well-demonstrated involvement of both interleukin 2 (IL-2) and interleukin 12 (IL-12) in the activation of host anti-cancer response, the knowledge of IL-2-IL-12 interactions has still to be better investigated." (PMID 9667674, 1998). "In this review we shall discuss the biological rationale and the clinical findings obtained using Interleukin 2 (IL2)-based immunotherapy in the management of cancer patients." (PMID 1457368, 1992). "We have assayed TNF and sTNFR-1 and 2 in the plasma of advanced cancer patients, before and during treatment with IL-2." (PMID 1333789, 1992). "Interleukin-2 (IL-2) is one of the most well-known cytokines used in cancer immunotherapy." (PMID 41355950, 2026). "Furthermore, Angelica sinensis improves hematopoiesis, enhances IL-2 production, and protects lymphocytes from chemotherapy-induced apoptosis, potentially maintaining immune homeostasis during cancer treatment." (PMID 41304903, 2025). "Notably, the use of low doses of IL-2 preferentially activates Treg cells, resulting in the inhibition and weakening of anti-cancer cytolytic responses." (PMID 39852848, 2025). "Notably, a recent effort to exploit CD25-biased IL-2 signaling in cancer immunotherapy involved the development of an IL-2/CD25 FP, which forms inactive head-to-tail transdimers that slowly dissociate into monomeric, biologically active units." (PMID 40789741, 2025).
cancer (continued). "With sustained innovation and rigorous clinical evaluation, IL-2 immunocytokines could provide durable responses and significantly improve survival outcomes for patients across a wide range of cancers." (PMID 39852848, 2025). "Notably, the construct containing GM-CSF as an adjuvant elicited a higher frequency of CTLs and a more prolonged memory response compared to the construct with IL-2, highlighting its potential as an effective cancer vaccine." (PMID 40599850, 2025). "Opposite results were instead obtained by the culture of Caki-1 cells with IL-2 (0.08 μg/mL and 0.4 μg/mL), indicating that IL-2 may also positively influence the viability and proliferation of the cancer cells." (PMID 41150778, 2025). "In addition, prodrugs of various cytokines including IL-2, IL-12 and IFNα2b were exploited to treat cancers." (PMID 41333471, 2025). "Small hydrophobic liposomes carrying IL-2 showed enhanced distribution and therapeutic efficacy in treating metastases by extending the time IL-2 circulation time, which could lead to fewer injections and improved cancer treatment outcomes." (PMID 40143046, 2025). "Among the various CD4+ T cell subtypes that regulate immune responses, the CD4+ T helper 1 (Th1) subset, which produces interferon (IFN)γ, tumor necrosis factor alpha (TNF-α), and interleukin-2 (IL-2), plays a central antitumor role by orchestrating cell-mediated immunity against cancer." (PMID 40543509, 2025). "Importantly, in the context of cancer immunotherapy, IL-2/CD25 FP was found to amplify vaccine-induced, neoantigen-specific CD4+ and CD8+ T cell responses, thereby enhancing antitumor immunity." (PMID 40789741, 2025). "Next, we grouped them into cytokines associated with pre-cancer or the initiation stage of HCC (IL-6, TGF-β, MCP-1, FGF2, IL-2, IL-8, IL-12p40, IL-12p70, IL-18, IP-10, TNF-α, and IFN-γ), the early stage of HCC (OPN, GDF-15, RANTES, and VEGFA), and the advanced stage of HCC (IL-10, and MIP-3)." (PMID 41219858, 2025). "Manipulating IL‐2 levels in patients is a focus of immunotherapeutic approaches, ranging from inhibition of IL‐2 for immunosuppression to its application as a vaccine adjuvant in cancer therapies." (PMID 41190418, 2025). "Cytokines, such as interleukin-2 (IL-2), also play a crucial role in cancer immunotherapy." (PMID 39808627, 2025). "Neither stress nor cancer caused any significant changes in IL‐2 or IL‐4 concentrations in the mouse brain." (PMID 40172096, 2025). "IL2 supports T-cell proliferation, survival, and differentiation, whereas IFNγ enhances antitumor immunity by promoting antigen presentation and by directly killing cancer cells." (PMID 39301613, 2025). "Additionally, compared to free IL-2, the CBD-IL-2 fusion protein showed enhanced antitumor effects across various cancer models and significantly reduced systemic toxicity." (PMID 40557148, 2025). "For example, it was revealed that cancer cells under stress conditions may release proinflammatory cytokines, such as IL-2, or IL12, that enhance anticancer immunity." (PMID 41294803, 2025). "Nevertheless, we still do not know about which signaling pathways may be activated or blocked upon IL-2 binding to the IL-2 receptor subunits in RCC, as well as how IL-2-concentration-dependent actions may work in cancer cells." (PMID 41150778, 2025). "Building on this approach, VSV engineered to express IL-2 or IL-2 mimics has been shown to act as a potent adjuvant for cancer vaccination, locally stimulating T and NK cells while avoiding the systemic toxicity of recombinant cytokines (Clinical Trial NCT02285816)." (PMID 41294689, 2025). "Interleukin 2 (IL-2), originally described as the main T-cell growth factor, has been used in standard high doses to activate cytotoxic T cells and natural killer cells in cancer therapy." (PMID 40615880, 2025). "However, these A-NK cells are terminally differentiated, unresponsive to IL-2, prone to apoptosis, and are ineffective in cancer therapy." (PMID 41907300, 2025).
cancer (continued). "Additionally, cytokine therapies (such as IL-2 and interferons) and cancer vaccines are part of immunotherapy, stimulating the immune system to recognize and destroy cancer cells." (PMID 40136430, 2025). "IL2 is the first effective cytokine used in human cancer immunotherapy." (PMID 41050655, 2025). "For immunotherapy of cancer, γδ T cells can be stimulated by aminobisphosphonates or natural or synthetic phosphoantigens, known to stimulate the Vy9Vδ2 T cells, and an addition of co-stimulators like interleukin 2 (IL-2)." (PMID 41369406, 2025). "A potential explanation for this discrepancy is different expression levels and epigenetic modifications controlling the expression of cereblon, Ikaros, and Aiolos, between cancer cell lines and primary cells, as well as differing downstream IL-2-mediated effects following pomalidomide treatment." (PMID 39902962, 2025). "This medicine also employs LD or ULD of IFN-α and IL-2 in association with other actives, such as TNF-α at 5 CH, and it could be seen as an interesting immunotherapy adjuvant drug in the context of cancer treatments." (PMID 40362536, 2025). "O.B. is a shareholder of Anaveon AG, developing CD122-biased IL-2 immunotherapy for cancer." (PMID 40502703, 2025). "Accordingly, a combination approach involving IL-10 and C3aR/C5aR antagonists could serve as an effective therapeutic strategy for immune-resistant cancers, particularly when augmented with the addition of IL-2 [IL-10 + IL-2 + C3aR/C5aR signaling blockade]." (PMID 40149345, 2025). "Similarly, co-treatment with A. muciniphila strengthened IL-2 antitumor effects in certain cancer models." (PMID 40104597, 2025). "Our research contributes to the expanding field of cancer therapies by analyzing immune changes in the peripheral blood at the single-cell level in patients treated with the oncolytic adenovirus TILT-123 coding for IL2 and TNFα." (PMID 40211048, 2025). "Notably, IFN-α and IL-2 have received FDA approval for cancer treatment, while others remain under investigation in preclinical models and ongoing clinical trials." (PMID 40149345, 2025). "Thus, identifying peptides or antigenic regions that can boost the production of IL-2 would become an important consideration while designing cancer treatment regimens and vaccine candidates." (PMID 40670434, 2025). "PD-1 blockade in combination with IL-2 administration is an emerging approach in treating cancer patients, in which IL-2 improves PD-1 blockade therapy through skewing the differentiation program of PD-1+TCF1+ stem-like CD8+ T cells away from T cell exhaustion, while instead toward effector T cells." (PMID 40759573, 2025). "Additionally, these extracts and their active compounds demonstrate cancer prevention properties by inhibiting the production of IL-2, TNF-α, and NO." (PMID 40022126, 2025). "IL-2 has demonstrated potential in treating various cancers." (PMID 40636453, 2025). "IL-2 marked a milestone as the initial immunotherapy to gain approval for cancer treatment." (PMID 40837119, 2025). "Moreover, the concomitant expansion of Treg cells on IL-2 therapy also raises questions as to its suitability for cancer immunotherapy." (PMID 40789741, 2025). "Moreover, VHH can be fused with cytokines to construct immunocytokines, such as IL2 and TNF-α, for anti-cancer treatments, which can overcome the adverse effects caused by using cytokines as monotherapy." (PMID 40358697, 2025). "It has been demonstrated that PD-1 blockade reinvigorates IL-2 production in T cells, and this is an important mechanism for the effectiveness of cancer immunotherapies, as IL-2 neutralization or CD25 blockage strongly diminishes the antitumor efficacy of PD-1 blockade." (PMID 40789741, 2025). "During acute infections, elevated levels of IL-2 promote the development of effector T cells; however, during chronic infections and cancer, high levels of IL-2 may lead to T cell apoptosis." (PMID 40428394, 2025).
cancer (continued). "Moreover, the liposomal encapsulation of IL-2 has also been demonstrated to improve its therapeutic effectiveness in treating diseases such as cancer and acquired immunodeficiency syndrome by extending its half-life and minimizing related side effects." (PMID 40143046, 2025). "Recent clinical studies have indicated that the combination therapy of IL2 with peptide vaccines had increased objective responses in cancer patients compared to IL2 alone, demonstrating that the monotherapy of IL2 can be enhanced by synthetic peptide cancer vaccines." (PMID 41050655, 2025). "Furthermore, the sophisticated design markedly diminished IL-2–related systemic toxicity, rendering it a promising option for cancer immunotherapy." (PMID 40009662, 2025). "Similarly, IL-2 can exert different effects on the immune system depending on the dose, but the high-dose regimen is known to be the most effective in inducing cancer regression." (PMID 40107242, 2025). "In some cancer patients, IL-2 may induce excessive immune activation, leading to systemic inflammatory responses and fatigue." (PMID 39980555, 2025). "However, IL-2 is only effective against cancer at high doses, due to its weaker interaction with dimeric IL-2R-expressing NK and effector T cells compared with trimeric IL-2R-expressing Treg cells, as well as the cytokine’s extremely short half-life." (PMID 40789741, 2025). "Notably, IL-2 was the first interleukin approved by the U.S. FDA as a cancer immunotherapeutic agent for metastatic renal cell carcinoma and metastatic melanoma." (PMID 40006624, 2025). "Interleukins, such as IL-2, IL-12, IL-15, IL-18, and IL-21, glucocorticoids, such as cortisone acetate and hydrocortisone, and ascorbic acid can promote the ex vivo proliferation of NK cells in healthy people or cancer patients." (PMID 39286242, 2024). "The critical role of the IL-2 signaling pathway in various cancers has been extensively studied." (PMID 38915471, 2024). "IL-2, IL-12, IL-15, IL-18, and IL-21 could promote NK cells entry into S and G2/M phases of the cell cycle in cancer patients or healthy subjects, and thus have been used to induce ex vivo NK cell proliferation." (PMID 39286242, 2024). "Based on the synergy between TET2 to IL-2/STAT5A signaling, we further examined whether VC enhanced the efficacy of anti-PD-L1 and IL-2 combination therapy, which is a potentially promising candidate for cancer therapy." (PMID 38177099, 2024). "In addition to its toxicity, IL-2 administration also leads to the expansion of Tregs in the blood of treated cancer patients, which can potentially limit the anti-tumoral activity of IL-2 treatment." (PMID 39114660, 2024). "IL-2 and interferons are the most important examples of cytokines used in cancer immunotherapy." (PMID 39015563, 2024). "IL-2 is crucial for T and NK cell expansion and maturation as well as regulatory T cells function, and has also been proposed as an immunotherapeutic drug against certain cancers." (PMID 39315059, 2024). "Of particular interest is IL‐2, which was the first cytokine approved for human cancer therapy." (PMID 38975278, 2024). "The use of allogeneic NK cell therapies from healthy donors has demonstrated favorable clinical efficacies in treating diverse cancers, particularly hematologic malignancies, but it requires cytokines such as IL-2 to primarily support NK cell persistence and expansion." (PMID 38698855, 2024). "For the other NSDTRs with cancer the levels of IL-2 were 1.1–48.8 ng/ml." (PMID 38773194, 2024). "IL-2 is one of the most commonly used cytokines in combination with cancer vaccines." (PMID 39872522, 2024). "High neutrophil levels in tissues secrete numerous inflammatory mediators like vascular endothelial growth factor (VEGF), tumor necrosis factor-a (TNF-a), interleukin-2 (IL-2), interleukin-10 (IL-10), and interleukin-6 (IL-6) which creates a suitable environment for cancer progression." (PMID 38166889, 2024).
cancer (continued). "Although FDA approved two recombinant cytokines, Interferon (IFNA) and Interleukin-2 (IL-2), as cancer immunotherapy drugs, the application of cytokines in immunotherapy still encounters many barriers and limitations, due to their pleiotropy, off-target effects, and short half-life in circulation." (PMID 39080467, 2024). "This circuit induces interleukin-2 (IL-2) in response to cancer antigens." (PMID 38491394, 2024). "Finally, SBsib-711 putatively indices IL-2 production and is preferred to recombinant IL-2 in cancer immunotherapy." (PMID 38399416, 2024). "Initially used in oncology, IL-2 has demonstrated significant benefits in patients with cancer." (PMID 39720733, 2024). "However, there have been major limitations associated with this therapy due to systemic toxicity, which has prevented many cancer patients from benefiting from IL-2 treatment." (PMID 38831884, 2024). "Moreover, our study demonstrates that live L. mesenteroides induces Jurkat T cells to secrete IFN-γ and IL-2, signifying its capability to activate T cells and bolster their role in eliminating cancer cells." (PMID 38755413, 2024). "However, although both THT and i.t. immunotherapies like IL-2 have individually shown promise in cancer treatment, the mechanism of their synergistic potential remain largely unexplored." (PMID 39872527, 2024). "The historical success of IL-2-based therapies has been instrumental in advancing cancer treatment." (PMID 38545115, 2024). "There is a possibility that activated NK cells stimulate the resting host immune system in the body through direct cell–cell interactions and/or their production of cytokines, such as IFN-γ and IL-2, especially in hematological and/or virus-related malignancies." (PMID 40729303, 2024). "IL-2 is one of the first approved cytokines for cancer immunotherapy." (PMID 38337114, 2024). "TILs can be isolated from cancer biopsies and expanded in interleukin −2 (IL2)-conditioned media." (PMID 40276485, 2024). "Furthermore, ESCO2 seemed to participate in the modulation of cancer inflammation, such as IL2 STAT5 signaling." (PMID 38605349, 2024). "This shows that combining IL-2 with drugs inhibiting TGF-β2 may be a favorable approach for treating cancer." (PMID 39272802, 2024). "Furthermore, numerous reports have emphasized the significance of the immunomodulatory gene IL-2 in cancer treatment and autoimmune diseases." (PMID 39308669, 2024). "Furthermore, the clinical administration of high IL-2 doses has demonstrated compelling evidence of cancer regression in patients with metastatic malignancies 52,53." (PMID 38617537, 2024). "Aldesleukin dosed as a single agent in patients with cancer has been associated with manifestations of CRS, raising the concern that combining IL-2 with checkpoint inhibitors may lead to increased severity of CRS." (PMID 39320047, 2024). "Administration of AII in the vicinity of cancer cells in patients might be problematic, but our data suggests that this may in part be circumvented by co-administration of cytokines such as IL2 or IL15." (PMID 38184565, 2024). "IL-2”), have demonstrated efficacy in enhancing the body's immune response against cancers." (PMID 39872527, 2024). "Moreover, CD8+ T cell-derived exosomes tethered with both anti-epidermal growth factor receptor (EGFR) antibodies and IL-2 via MTFP specifically induced EGFR-positive cancer cell death through immune activation." (PMID 38172594, 2024). "The optimal method for pediatric cancer patients requires testing and alternative cytokines, such as IL-15, may be more effective than IL-2." (PMID 39310750, 2024). "The data obtained from this study further supports the therapeutic potential of the combination therapy, indicating that CU06-1004 may complement the anti-cancer efficacy of IL-2 treatment." (PMID 37711172, 2023).